HDAC9 (histone deacetylase 9)
Diseases named in the same sentence as HDAC9 in open-access papers (continued):
Sharing a sentence is not in itself a finding about the gene and the disease.
viral infection (26 papers, 2012 to 2025). "HDACs are implicated in viral infections; for instance, Marek’s disease virus (MDV) interacts with HDAC1 and HDAC2 to facilitate their degradation, while the knockout of HDAC9 enhances foot-and-mouth disease virus (FMDV) replication." (PMID 40938964, 2025). "During viral infection, histone deacetylase 9 (HDAC9) deacetylates tank-bound kinase 1 (TBK1) to activate TBK1 phosphorylation, leading to an increase in type I IFN." (PMID 37396372, 2023). "The cytopathic effect (CPE) could be observed at 4 h after virus infection, and more CPE was observed in HDAC9-KO-1 cells." (PMID 35250927, 2022).
autoimmune disease (25 papers, 2012 to 2025). A disorder resulting from loss of function or tissue destruction of an organ or multiple organs, arising from humoral or cellular immune responses of the individual to their own tissue constituents. "In the MLR/lpr mouse, knock-out of Hdac9 resulted in a prolonged survival and decrease in autoimmune disease progression." (PMID 30792714, 2019). "Taken together, HDAC9 showed to promote the development of autoimmune disease via its function in both Teff and Treg cells." (PMID 30792714, 2019). "An important role for HDAC9 in the development of autoimmune disease was demonstrated in several studies." (PMID 30792714, 2019). "HDAC9 inhibition could therefore be of important therapeutic potential in the treatment of autoimmune diseases such as JIA." (PMID 30792714, 2019). "Of 223 hypomethylated regions identified, several were in promoters of autoimmune disease GWAS loci (ARID5B, CD69, HDAC9, IL7R, TNIP1 and TRAF1)." (PMID 32231389, 2020). "The inhibition of HDAC9 could therefore be of therapeutic interest in the context of autoimmune diseases such as JIA, however it's specific role in arthritis had not been investigated yet." (PMID 30792714, 2019).
endometrial cancer (25 papers, 2010 to 2025). Primary or metastatic malignant neoplasm involving the endometrium (mucous membrane that lines the endometrial cavity). "A recent study demonstrated that miR-101-3p prevented retinoblastoma cell proliferation by targeting EZH2 and HDAC9, prevented autophagy in endometrial cancer cells by targeting EZH2 and inhibits invasion and metastasis in renal cell carcinoma by Targeting EZH2." (PMID 36873948, 2023).
ischemia (22 papers, 2012 to 2025). A hypoperfusion of the BLOOD through an organ or tissue caused by a PATHOLOGIC CONSTRICTION or obstruction of its BLOOD VESSELS, or an absence of BLOOD CIRCULATION. "Moreover, as per our findings, ischemia led to an increase in the HDAC9 expression in the brain of wild type mice, while the loss of HDAC9 was observed to suppress the release of IL-1β, IL-6, IL-18, and TNF-α in the mouse cortex, hippocampus, and hypothalamus after I/R injury." (PMID 33584204, 2020). "Another HDAC, HDAC9, affected EC dysfunction and permeability dysfunction in oxygen-glucose deprivation-induced ischemia in the cerebral hemisphere." (PMID 35529430, 2022).
lupus (22 papers, 2014 to 2025). "HDAC9 deficiency in MRL/lpr mice has been shown to reduce lupus symptoms and increase survival rates compared to HDAC9 intact MRL/lpr mice." (PMID 30545086, 2018). "Our results are also in agreement with a recent study utilizing an MRL/lpr GEM model of systemic lupus erythematosus with HDAC9 deficiency." (PMID 27799148, 2016).
Sepsis (22 papers, 2010 to 2025). Sepsis is defined as life-threatening organ dysfunction caused by a dysregulated host response to infection. "In sepsis-induced acute lung injury (SI-ALI), PDK4 hyperactivation drives excessive lactate production in epithelial cells, triggering AARS1/HDAC9-mediated LPCAT2 lactylation." (PMID 41057687, 2025).
Insulin resistance (21 papers, 2012 to 2025). Increased resistance towards insulin, that is, diminished effectiveness of insulin in reducing blood glucose levels. "In contrast, transgenic overexpression of HDAC9 induces adipocyte hypertrophy and insulin resistance in aging mice." (PMID 40002674, 2025). "We report that global transgenic overexpression of Hdac9 is sufficient to promote adipocyte hypertrophy, hepatic steatosis, insulin resistance, and glucose intolerance in aging mice fed a standard laboratory diet." (PMID 38672510, 2024). "While young (18-week-old) HDAC9 TG mice appeared metabolically healthy, middle aged (40-week-old) HDAC9 TG mice exhibited impaired glucose tolerance and insulin resistance, along with increased lipid accumulation in the liver." (PMID 38672510, 2024). "We previously reported that Hdac9 expression in adipose tissue is increased in obese high fat fed-mice, in conjunction with adipocyte hypertrophy, ectopic lipid accumulation in the liver, insulin resistance, and glucose intolerance." (PMID 38672510, 2024). "In order to test whether overexpression of HDAC9 is sufficient to promote adipose tissue dysfunction and insulin resistance, we developed a global HDAC9 transgenic mouse model." (PMID 38672510, 2024). "The model proposed based on our data from statin-induced insulin resistance is that hypomethylation of the HDAC9 promoter is correlated with HDAC9 gene expression, which acts as a transcriptional repressor to ABCG1 expression and thereby adipocyte differentiation and metabolic dysfunction." (PMID 32410704, 2020).
lung adenocarcinoma (21 papers, 2013 to 2024). A carcinoma that arises from the lung and is characterized by the presence of malignant glandular epithelial cells. "The GO term ‘protein modification process’ includes histone deacetylase 9, a known tumor suppressor, the downregulation of which has been reported to promote disease progression, particularly in lung adenocarcinoma." (PMID 37667226, 2023). "An integrative analysis of 60 paired lung adenocarcinoma specimens using a genome-wide human SNP array revealed that the aberrant HDAC9 SNP rs10248565 on chromosome 7p21.1 may serve as a biomarker for lung adenocarcinoma in non-smoking women." (PMID 34318404, 2021). "Although more studies are still needed, SNP rs10248565 in HDAC9 may be one of the potential biomarkers for lung adenocarcinoma in non-smoking women." (PMID 24650256, 2014).
diabetic nephropathy (18 papers, 2013 to 2025). "In vivo and in vitro experiments in diabetic nephropathy models have demonstrated that HDAC9 can induce podocyte apoptosis and renal injury through the JAK2/STAT3 pathway." (PMID 38528189, 2024).
breast tumors (17 papers, 2013 to 2024). "Similarly, in human breast tumor samples, a meta‐analysis revealed that high HDAC9 mRNA levels were associated with decreased overall survival in tamoxifen‐treated patients." (PMID 31099456, 2019). "The decreased ERα expression in MCF7 cells upon HDAC9 overexpression, even at moderate levels, may be one of the mechanisms by which deregulated HDAC9 expression is linked to OHTam resistance in ERα‐positive breast tumor cells." (PMID 31099456, 2019). "The prognostic significance of HDAC9 expression in breast tumors and its relation to the resistance of the tumor to treatment will be important issues." (PMID 26930713, 2016). "In a set of 35 breast tumor cell lines classified as luminal (n=19) or basal (n=16), RT-qPCR quantification confirmed higher levels of HDAC9 mRNA levels in basal cells as compared to luminal ones (p<0.0001)." (PMID 26930713, 2016). "Alternatively, differences in transcription factors and/or cofactors may be involved in HDAC9 gene transcription between the two groups of breast tumor cells." (PMID 26930713, 2016). "We show here that class IIa HDAC9 may be another regulator of SOX9 expression in breast tumor cells." (PMID 26930713, 2016). "Interestingly, increased expression of HDAC9 was also observed in the MCF10 cell model of breast tumor progression." (PMID 26930713, 2016). "As HDAC9 was found to be overexpressed in the most aggressive breast tumor cells, we wondered what consequences HDAC9 overexpression could have on luminal cells behavior." (PMID 26930713, 2016). "In the later cohort, Pearson's analysis confirmed a strong correlation between HDAC9 and SOX9 expression in breast tumors (r=0.526, p<0.00001)." (PMID 26930713, 2016). "In this cohort, HDAC9 mRNA levels were significantly higher in ERα‐negative than in ERα‐positive breast tumors (P < 0.0001)." (PMID 31099456, 2019). "Conversely, HDAC9 mRNA was strongly overexpressed in OHTam‐resistant MCF7 cells and in ERα‐negative breast tumor cell lines." (PMID 31099456, 2019).
autism (16 papers, 2014 to 2024). Persistent deficits in social interaction and communication and interaction as well as a markedly restricted repertoire of activity and interest as well as repetitive patterns of behavior. "Increase in HDAC9 copy number has been correlated with an increased risk of autism, whereas according to the Simons foundation autism research initiative (SFARI) and Autism KB databases for genetic variants associated to ASD risk, different KATs and KDACs are associated with ASD risk." (PMID 28161493, 2017).
liver fibrosis (16 papers, 2013 to 2025). "Pirfenidone, but also LBH589, reduced significantly the protein expression of HDAC1, HDAC2, and of a ~66 kDa isoform of class-IIa-HDAC9, a HDAC comprising several alternatively spliced isoforms with profibrotic function in liver fibrosis." (PMID 30481203, 2018). "Increased presence of HDAC9 has been reported to play a profibrotic role in the activation of hepatic stellate cells (HSC) during liver fibrosis in vivo, whereas knockdown of HDAC9 decreased TGF-β1-induced fibrogenic gene expression in the human HSC cell line LX-2." (PMID 30481203, 2018).
Hyperglycemia (15 papers, 2015 to 2025). An increased concentration of glucose in the blood. "The differential gene ontology (GO) analysis showed the mechanism of ameliorated hyperglycemia and liver metabolic disorders was related to histone deacetylation, and Hdac9 was significantly downregulated by acetate." (PMID 39741391, 2025).
acute lymphoblastic leukemia (14 papers, 2010 to 2025). Leukemia with an acute onset, characterized by the presence of lymphoblasts in the bone marrow and the peripheral blood. "Likewise, low HDAC3, HDAC7 and HDAC9 expressions has been associated with poor prognosis and survival in childhood acute lymphoblastic leukemia (ALL)." (PMID 33024443, 2020).
COVID-19 (14 papers, 2021 to 2024). A disease caused by infection with severe acute respiratory syndrome coronavirus 2. "The rs7795433 SNP of the HDAC9 gene (7q21.1) showed the strongest association with COVID-19 vaccination under the additive model (OR = 5.63; p = 3 × 10−5)." (PMID 38932355, 2024). "Nevertheless, our study is significant in identifying candidate gene HDAC9, which is associated with differences in antibody production after COVID-19 mRNA vaccination, focusing on the Korean population." (PMID 38932355, 2024). "The HDAC9 gene has been identified to play a role in antibody generation after COVID-19 vaccination, with a higher likelihood of increased antibody production in the AA allele group." (PMID 38932355, 2024). "Specifically, several Notch-related genes were upregulated in COVID-19 samples for all three organs, including HDAC9, a selective regulator of Notch, FBXW7, a regulator of angiogenesis through Notch, and TBLR1, an indirect Notch regulator through degradation." (PMID 37830426, 2023).
head and neck cancer (14 papers, 2008 to 2025). A primary or metastatic malignant neoplasm affecting the head and neck. "In head and neck malignant tumors, overexpression of HDAC9 promotes carcinogenesis by targeting the transcription factor MEF2D and the proapoptotic MEF2 target, NR4A1/Nur77." (PMID 40145017, 2025).
oral squamous cell carcinoma (14 papers, 2008 to 2026). "Overexpression of HDAC9 has been linked to poor prognosis of oral squamous cell carcinoma by targeting MEF-2D and repressing expression of MEF-2-dependent genes." (PMID 31105874, 2019). "In pancreatic ductal adenocarcinoma, high HDAC9 expression was significantly related to poor prognosis, and overexpression of HDAC9 promoted progression of the malignant phenotype of oral squamous cell carcinoma." (PMID 35239708, 2022).
retinoblastoma (14 papers, 2019 to 2025). A malignant tumor that originates in the nuclear layer of the retina. "HDAC9 overexpression contributes to the pathogenesis of retinoblastoma." (PMID 38920983, 2024). "HDAC9 expression is associated with cell proliferation in vitro, and its inhibition with cell arrest in the G1 phase is consistent with the reduction of Cyclin E2 and CDK2 expression in retinoblastoma cells." (PMID 37887350, 2023). "Additionally, upregulation of miR-101-3p has been reported to suppress EZH2 and HDAC9 expression, thereby inhibiting cell cycle progression in retinoblastoma cells." (PMID 37887350, 2023). "A recent study reported that miR-101-3p prevented retinoblastoma cell proliferation by targeting EZH2 and HDAC9." (PMID 34307682, 2021). "Additionally, miR-101 inhibits the proliferation of retinoblastoma cells by targeting EZH2 and histone deacetylase 9 (HDAC9)." (PMID 36497343, 2022).
memory impairment (13 papers, 2014 to 2025). "In general, our results reported HDAC9‐mediated CaM deacetylation induced memory impairment in AD, and discovered that abnormally reduced plasma CaM acetylation may be a new early diagnostic marker for AD, and indicated that HDAC9 or CaM acetylation may become potential therapeutic targets for AD." (PMID 38421101, 2024). "Together, these results provided evidence for a role of HDAC9‐mediated CaM deacetylation in memory impairment of AD, and revealed dynamic CaM acetylation in the pathogenesis of AD." (PMID 38421101, 2024). "In AD, HDAC9-mediated CaM deacetylation induced hippocampus-dependent memory impairment." (PMID 40868317, 2025). "HDAC9‐mediated CaM deacetylation induces memory impairment in AD, HDAC9, or CaM acetylation may become potential therapeutic targets for AD." (PMID 38421101, 2024).
pancreatic ductal adenocarcinoma (13 papers, 2013 to 2024). An infiltrating adenocarcinoma that arises from the epithelial cells of the pancreas. "Valproic acid targeting HDAC9, a known interactor of PKD1, restores ciliogenesis in pancreatic ductal adenocarcinoma cells." (PMID 32973177, 2020).
type 2 diabetes (13 papers, 2016 to 2025). "Thus, HDAC9-FoxO1 signalling axis is involved in regulating gluconeogenic transcription factors, gluconeogenesis, and HCV-induced type 2 diabetes." (PMID 28733598, 2017).
coronary artery disease (12 papers, 2015 to 2025). "The HDAC9 risk variant was also found to be associated with carotid intima-media thickness and coronary artery diseases, suggesting a role for HDAC9 in promoting atherosclerotic pathogenesis." (PMID 37120540, 2023). "The HDAC9 locus was subsequently also identified as a risk locus for coronary artery disease and pulse pressure." (PMID 27796860, 2016). "A genetic variant in HDAC9 is also associated with large vessel ischemic stroke, carotid atherosclerosis and coronary artery disease." (PMID 26488411, 2015). "Here, we applied this pipeline to understand a cluster of SNPs associated with coronary artery disease (CAD) within and immediately adjacent to the gene encoding HDAC9." (PMID 35714152, 2022). "Recent genome-wide association studies (GWAS) have indicated an association of histone deacetylase 9 (HDAC9) genetic variant with large-vessel stroke and coronary artery disease, among the European population." (PMID 27642596, 2016).
periodontitis (12 papers, 2015 to 2026). An acute or chronic inflammatory process that affects the tissues that surround and support the teeth. "In our study, we showed that histone modifications are involved in periodontitis and we showed mi-RNA participation in the regulation of HDAC9 under inflammatory conditions and rescued the tooth loss in periodontitis by HDI." (PMID 29691366, 2018). "We first examined the association of HDAC9 with miR-17~92a in PDLSCs of periodontitis patients." (PMID 29691366, 2018). "HDAC9 RNA expression levels appear to be significantly increased in PDL stem cells under inflammatory conditions driven by periodontitis or exposure to TNFα, which impaired osteogenic capacity in vitro." (PMID 36291079, 2022). "Consistent to HDAC9 function, PDLSCs from periodontitis tissue down regulated miRNA-17 level." (PMID 39959357, 2025). "Besides, it was reported that HDAC9 can deacetylate the histones H3K14 and H4K16, and afterward inhibit the family of microRNA17‐92, leading to a decrease in the osteogenic differentiation of PDLSCs in periodontitis." (PMID 37021521, 2023).
acute promyelocytic leukemia (10 papers, 2010 to 2025). An aggressive form of acute myeloid leukemia (AML), characterized by arrest of leukocyte differentiation at the promyelocyte stage, due to a specific chromosomal translocation t(15;17) in myeloid cells. "Moreover, HDAC9 promoted ALT pathway by increased formation of ALT-associated promyelocytic leukemia nuclear bodies in ALT positive cells." (PMID 33802026, 2021).
allergic disease (10 papers, 2018 to 2025). An immune response that occurs following re-exposure to an innocuous antigen, and that requires the presence of existing antibodies against that antigen. "Then we established CD45.1/2+ sh-Ctrl/Hdac9 OT-II cell transfer allergy model." (PMID 34006836, 2021).
chronic kidney disease (10 papers, 2013 to 2024). Impairment of the renal function secondary to chronic kidney damage persisting for three or more months. "However, whether HDAC9 is a universal pathogenic factor contributing to kidney fibrosis under different pathophysiological conditions in chronic kidney disease keeps unclear." (PMID 37230975, 2023). "For calcification located in the medial vessel wall, BHB has been reported to suppress this process by enhancing autophagy in VSMCs and downregulating histone deacetylase 9 (HDAC9) in rats with chronic kidney disease and C57BL/6J mice overloaded with vitamin D3." (PMID 39796543, 2024). "Pharmacological targeting of HDAC9 may be an effective innovative therapeutic strategy for patients with chronic kidney disease." (PMID 37230975, 2023). "In this study, our results showed that HDAC9 expression was significantly increased in fibrotic kidneys, especially in proximal tubules, from different mouse models of kidney fibrosis including AAN, UUO and ischemia-reperfusion injury (IRI)-induced chronic kidney disease." (PMID 37230975, 2023).
Autoimmunity (9 papers, 2011 to 2024). The occurrence of an immune reaction against the organism's own cells or tissues. "Strikingly, 20 of the 21 significant SNPs resided in Histone Deacetylase 9 (HDAC9), an enzyme linked to epigenetic control of gene transcription and previously proposed to be an epigenetic switch for T-cell-mediated autoimmunity." (PMID 38212708, 2024).
leiomyosarcoma (9 papers, 2017 to 2025). An uncommon, aggressive malignant smooth muscle neoplasm, usually occurring in post-menopausal women. "HDAC9 can influence H3K27 acetylation in leiomyosarcoma and enhance cell survival by repressing Fas cell surface death receptor (FAS) transcription." (PMID 35008848, 2021). "Interestingly, it has been described that MEF2D binds to the promoter and regulates the expression of Hdac9 during muscle differentiation, and in leiomyosarcoma cells." (PMID 35076395, 2022). "HDAC4 and HDAC9 are upregulated in leiomyosarcoma, and HDAC2 is activated in liposarcomas." (PMID 35008848, 2021).